MAPT (microtubule associated protein tau)
Diseases named in the same sentence as MAPT in open-access papers (continued):
Sharing a sentence is not in itself a finding about the gene and the disease.
tauopathies (continued). "The number of treatments studied in transgenic and knock‐in MAPT mouse models of tauopathy has increased steadily since 2004 as more of these mouse models have become available since early published descriptions in 1999." (PMID 40826256, 2025). "Given that our search started with the year that the first of the 27 single transgene/knock‐in/knock‐out MAPT mouse models was developed, this review is a nearly comprehensive compilation of therapeutic studies in tauopathy mice." (PMID 40826256, 2025). "Together, this mutant MAPT engineered series will be a valuable tool for elucidating the molecular mechanisms driving neurodegenerative tauopathies within the unique genetic context of African ancestry." (PMID 40219788, 2025). "A range of MAPT KI mutant mice modelling these aspects of human tauopathies will be invaluable to address pathomechanistic questions." (PMID 39719507, 2025). "Among the HSP-regulated client proteins, the microtubule-associated protein Tau (MAPT, Tau) is the most representative, and its oligomeric aggregation is a key driver in the development of neurodegenerative diseases (i.e. Tauopathy)." (PMID 41488136, 2025). "In our study, we directly analyzed CNVs across 14 exons of the MAPT gene, motivated by its well-established role in tauopathies and early-onset neurodegeneration." (PMID 40725212, 2025). "MAPT mouse models of tauopathy have been essential for testing potential therapeutic strategies and garnered many positive results, but translating these results to effective human treatments remains a significant challenge." (PMID 40826256, 2025). "The P301L missense mutation in MAPT is causally associated with human FTLD and has been extensively studied in various tauopathy models." (PMID 37955806, 2024). "As a final point, the investigation into MAPT gene expression in fibroblasts offers a promising avenue for diagnosing tauopathies and distinguishing them from other neurodegenerative diseases." (PMID 39766775, 2024). "More than a decade ago, studies indicated that in several primary tauopathies the regulation of MAPT splicing is altered and that misspliced isoforms are differentially incorporated into neurofibrillary tangles (NFTs) and pathogenic inclusions." (PMID 38170841, 2024). "The aggregation-prone protein tau, encoded by the MAPT gene, has been found to interact with SQSTM1 in both human brain tissue with tauopathies and in murine transgenic tauopathies models." (PMID 39098523, 2024). "It is primarily expressed in neurons and a small amount in mature oligodendrocytes (OLs) in the central nervous system (CNS), and more than 30 different familial mutations in the MAPT gene cause frontotemporal dementia (FTD) and other tauopathy." (PMID 39596399, 2024). "In the case of hereditary secondary tauopathies, MAPT abnormalities can be involved as a disease modifying or risk factor, but TAU pathology appears to be a consequence of the known disease-causing pathology." (PMID 38554150, 2024). "Comprehending the functional implications of MAPT variations opens opportunities for tailored treatment therapies and sheds light on the molecular mechanisms driving tauopathies." (PMID 38607741, 2024). "The human MAPT-expressing P301S tauopathy mouse PS-19 model shows an aberrant expression of Bmal1 in the SCN." (PMID 38195580, 2024). "Primary tauopathies can be categorized using various criteria, such as their sporadic or familial nature based on mutations in the MAPT gene, or by the predominant TAU isoforms involved, resulting in 3R, 4R, or 3R/4R tauopathies." (PMID 38554150, 2024). "An imbalance of TAU isoforms (especially the 4R/3R ratio) in favor of the 4R isoform due to altered MAPT splicing (increased exon 10 inclusion) is reported in HD similar to a subset of primary tauopathies." (PMID 38554150, 2024). "Important progress has also been made by generating humanized mice expressing the human sequences of Aβ or MAPT as in vivo models of tauopathy." (PMID 38450383, 2024).
tauopathies (continued). "Multiple animal models of tauopathy expressing mutant forms of MAPT recapitulate oligodendroglial tau inclusions with potential to cause degeneration/malfunction of oligodendrocytes and affecting the neuronal myelin sheath." (PMID 38994964, 2024). "In tauopathies, an elevation of lysosomal pH was observed in iPSC-derived neurons with IVS10 + 16/P301S mutations of MAPT at day in vitro (DIV) 65 compared with IVS10 + 16/WT control neurons." (PMID 37287072, 2023). "Tauopathies represent a heterogeneous group of around 20 neurodegenerative diseases characterized by abnormal deposition of MAPT in neurons and glial cells." (PMID 37047532, 2023). "Alternatively, rodents would overexpress a mutation (P301L or K369I) in the microtubule-associated protein tau (MAPT), resulting in destabilization of the microtubule network and tauopathies 26-29." (PMID 37554284, 2023). "All these diseases share the common feature of the accumulation of aggregates of hyperphosphorylated microtubule-associated protein tau (MAPT), which results in neurofibrillary tangles (NFTs), one of the hallmarks of AD, the most prominent tauopathy." (PMID 37895469, 2023). "Long-term follow-up of mutation carriers will help to establish a dynamic biomarker model for MAPT- or tauopathy-related FTLD, including CBF changes, tau accumulation, neuroinflammation, neurodegeneration and cognitive and linguistic impairments." (PMID 36707904, 2023). "The fE mice with or without Syn1-Cre were crossbred with mice expressing mutant 1N4R human microtubule-associated protein tau (MAPT) encoding the disease-associated P301S mutation (PS19 line), which has been widely utilized as a tauopathy mouse model." (PMID 37118426, 2023). "Those conclusions were based on the observed increase of new adult born OLs without net OL density change in another AD mouse model (J20 or PDGF-APPSw,Ind) and a mouse model of tauopathy (MAPT P301S)." (PMID 35465615, 2022). "Each of the tauopathies are pathologically defined by the progressive accumulation in the brain of MAPT proteins as complex fibrillar aggregates, and their incidence and prevalence are now known to correlate strongly with the degree of dementia." (PMID 35204666, 2022). "Mutations in the MAPT gene have been described, leading to frontotemporal dementia (FTD) or other tauopathies, and some mutations also act as risk factors for AD." (PMID 35203497, 2022). "There is a whole group of disorders that are characterized by the presence of abnormal MAPT aggregation, which are called tauopathies." (PMID 36078974, 2022). "Since basal levels of AT8 Tau phosphorylation were undetectable in WT mice, we used tissue from transgenic PS190/+ mice that express a mutant form of human Tau (MAPT P301S) associated with FTD and are a well-described animal model of tauopathy." (PMID 35501917, 2022). "As a novel in vivo platform for studying human tauopathy, human MAPT knock-in mice have been developed in which the entire Mapt gene including all exons and introns are humanized." (PMID 35431779, 2022). "FTD-Tau, accounts for 40% of all FTD cases and is characterized by the presence of cytosolic, hyperphosphorylated, insoluble filaments of the microtubule-associated protein Tau (MAPT) in neurons and glia (Tauopathy)." (PMID 35281504, 2022). "We also correlated results with other neurodegenerative diseases, including AD and a related tauopathy, frontotemporal lobar degeneration with microtubule associated protein tau mutations (FTLD-MAPT), to identify neurodegenerative disease-related changes." (PMID 34172091, 2021). "Each of the tauopathies are defined by the progressive accumulation in the brain of MAPT proteins as complex, multi-component fibrillar aggregates, and their incidence and prevalence correlate strongly with the degree of dementia." (PMID 35069109, 2021).
tauopathies (continued). "In the following years, a host of tauopathies were induced in WTs, from 3R and 4R tauopathies AD and PART, through to 4R tauopathies including aging-related tau astrogliopathy (ARTAG), GGT, PSP, CBD, AGD, and familial FTD linked to the P301L MAPT mutation." (PMID 34200180, 2021). "Thirdly, tauopathies have the smallest basal forebrain volumes, driven by both patients with FTDP-17 (i.e. MAPT mutations) and Pick's disease, whilst in the TDP-43 proteinopathies, lower volumes are driven by a decrease in those with type C pathology." (PMID 32143137, 2020). "Expression of human MAPT in the nervous system of the fruit fly, Drosophila melanogaster, recapitulates many key features of tauopathies, including misfolded/hyperphosphorylated Tau, age-dependent synaptic dysfunction and neuronal loss, and reduced survival." (PMID 32993812, 2020). "Tauopathies represent a heterogeneous group of around 20 different neurodegenerative diseases characterized by abnormal deposition of the MAPT in cells of the nervous system." (PMID 33100967, 2020). "In the human context—as briefly inventoried here—there are different tauopathies, but heterogeneity can also be evident within a given disease entity having the exact same MAPT protein coding sequence and recently illustrated for FTLD-MAPT-P301L cases." (PMID 33304310, 2020). "Tg mice expressing human MAPT (1N4R isoform) bearing the P301S missense mutation, termed PS19 (P301S Tg) mice, have become an indispensable tool in research on AD and related tauopathies." (PMID 32093751, 2020). "Our data provide some additional support for the association of MAPT genetic variation with tau burden, and more broadly reinforces prior work suggesting roles for MAPT in the pathophysiology of Alzheimer’s disease and other tauopathies." (PMID 33426524, 2020). "Our findings also indicate that similarities in MAPT haplotype risk-factor profile exist between CBD and the related tauopathy progressive supranuclear palsy, with H2, H1d, and H1c displaying associations with both diseases." (PMID 33287913, 2020). "This section provides a brief overview of tau protein, its isoforms generated from the MAPT gene, and their key roles in tauopathies." (PMID 33121065, 2020). "Tauopathies represent a heterogeneous group of around 20 neurodegenerative diseases characterized by abnormal deposition of the MAPT in neurons and glial cells." (PMID 33100967, 2020). "The predominant aggregation of certain MAPT (tau gene) isoforms, either the 4-repeat (4R tau) or the 3-repeat (3R tau) isoforms have been widely described in tauopathies." (PMID 32098280, 2020). "Noting these points and, because it is known that experimentally-tractable FTLD-MAPT tauopathy manifests in different cell populations sharing the same MAPT genotype, it is likely that aspects of the cell biology of tau remain to be discovered." (PMID 33304310, 2020). "In FTD and related tauopathies, in vivo findings with 18F-flortaucipir have been mixed, with some suggesting 18F-flortaucipir retention in areas of predicted pathology in CBS and MAPT mutation carriers." (PMID 30704514, 2019). "Variations in the microtubule-associated protein tau gene (MAPT) which encodes tau protein for microtubule stability and signal transduction, are well documented to be involved in typical tauopathies and dementia." (PMID 30708351, 2019). "Hyperphosphorylation of the microtubule-associated protein tau and its resultant aggregation into neurofibrillary tangles (NFT) is a pathological characteristic of neurodegenerative disorders known as tauopathies." (PMID 31780921, 2019). "MAPT gene silencing using antisense oligonucleotides or RNA interference are other promising future therapeutic strategies for tauopathies." (PMID 31695675, 2019). "Microtubule-associated protein tau (MAPT) hyperphosphorylation and aggregation, are two hallmarks of a family of neurodegenerative disorders collectively referred to as tauopathies." (PMID 30619849, 2018).
tauopathies (continued). "There is pathologic overlap between FTLD with MAPT p.R406W and other primary tauopathies, including PSP and CBD50." (PMID 30546007, 2018). "A gene our previous approach had not identified, and an example of coordination between coding exons, is MAPT, which forms the basis of all tauopathies." (PMID 29196558, 2018). "With the aim to generate improved translational human tauopathy models, we used ZFN technology to introduce the FTDP-17-associated MAPT IVS10+16 and P301S mutations into commercially available control hiPSCs (iPSC0028) from Sigma." (PMID 30057263, 2018). "Our results also indicate that the iPSC model of MAPT p.R406W has some correlation with PSP, implicating the ability of the iPSC model of MAPT p.R406W to capture disease mechanisms related to other primary tauopathies." (PMID 30546007, 2018). "To begin to address this question, we examined temporal expression of Gabbr1, Gabrb2, Gabrb3, and Gabrg2 in a mouse model of tauopathy that overexpresses human MAPT p.P301L37." (PMID 30546007, 2018). "For the AD-associated gene BIN1, we confirm coordinated splicing, and we can now appreciate coordination in MAPT—a gene central to tauopathies." (PMID 29196558, 2018). "Increases in midbrain and basal ganglia [18F]AV1451 uptake were also shown found in other 4R tauopathies such as PSP and in MAPT p.R406W mutation carriers." (PMID 30090966, 2018). "Here we address the effect of TREM2 deficiency on another cardinal aspect of neurodegeneration, intracellular neuronal aggregates of hyperphosphorylated microtubule associated protein tau (MAPT; tau), using the hTau mouse model of tauopathy." (PMID 29037207, 2017). "Increasing evidence suggests that hyperphosphorylation and aggregation of microtubule-associated protein tau (MAPT or tau) correlates with the development of cognitive impairment in Alzheimer’s disease (AD) and related tauopathies." (PMID 28367114, 2017). "Lastly, we showed that MAPT’s alternative promoter is active in brain tissues affected by the tauopathies AD and PSP." (PMID 28974731, 2017). "This study demonstrated improved survival and histopathology in a mouse model of tauopathy, and also showed tau protein reduction in CNS tissues and CSF in non-human primates following intrathecal bolus administration of ASOs targeting MAPT mRNA." (PMID 28982376, 2017). "The present study aimed to investigate the involvement of ER stress in AD-like outcomes in vitro, as measured by ATF4 and CHOP, and in vivo using experimental AD models of tauopathy (MAPT P301S) and excessive amyloidosis (APPSwe)." (PMID 28721361, 2017). "Tauopathy in the nucleus basalis of Meynert was strongly correlated with p-MAPT-positive axons in the fornix, suggesting that projections to the hippocampus also likely contribute to fornix tauopathy." (PMID 27793193, 2016). "The P301S transgenic model expressing the P301S mutant form of human MAPT, driven by mouse Prnp (prion protein promoter), exhibits many characteristics of human tauopathy, including neuronal tau inclusions and neurodegeneration." (PMID 27257626, 2016). "Recently, a rare MAPT p.A152T mutation was identified as a novel risk factor among patients diagnosed with PSP, AD, PD, CBD and unclassifiable tauopathy presenting with atypical clinical and neuropathological features." (PMID 26916334, 2016). "We performed correlation analyses of p-MAPT staining in the fornix and basal forebrain nuclei to further probe the tauopathy patterns in these interconnected structures." (PMID 27793193, 2016). "The overall genetic contribution of MAPT variants to LOAD risk appears to be modest, in contrast to primary tauopathies, where the H1 haplotype, for example, has an estimated OR of 5.5 from the PSP GWAS." (PMID 25324900, 2014). "Of the 13 cases with PEP and unclassifiable tauopathy we identified 1 case with both LRRK2 G2019S mutation and a heterozygous variant in MAPT exon 4 (c.370C>G, p.Q124E)." (PMID 23664753, 2013).
tauopathies (continued). "With this background, we determined to sequence the MAPT gene in our small series of cases with indeterminate tauopathies (eight cases)." (PMID 22595371, 2012). "Recently, an A152T variation in MAPT exon 7 was identified in a patient who had dementia and unclassifiable tauopathy." (PMID 22595371, 2012). "The microtubule-associated protein Tau (MAPT) is a major component of the pathogenesis of a wide variety of brain-damaging disorders, known as tauopathies." (PMID 22720188, 2012). "This biomarker combination can also detect a mixed 3R/4R tauopathy—similar to AD but without Aβ deposition—resulting from the rare MAPT R406W mutation." (PMID 40282991, 2025). "The revelation that mutations in the MAPT gene that encodes Tau can cause neuronal dysfunction, cognitive impairment and death in frontotemporal dementia (FTD) and PSP sufferers supported the importance of tauopathy as a significant class of NDDs." (PMID 40867577, 2025). "Despite their clinical differences, these disorders share key pathological hallmarks, such as the accumulation and aggregation of disease-specific proteins, for example tau (MAPT) in AD and other tauopathies and α-synuclein (SNCA) in PD and other synucleinopathies." (PMID 40498021, 2025). "Here, the identification of a MAPT mutation directly implicated tauopathy, supporting classification as a “non-AD dementia”." (PMID 41399730, 2025). "These examples show that although some frequently evaluated treatments that showed positive effects in multiple MAPT mouse models have proceeded to clinical testing for primary tauopathies, the outcomes of the clinical trials have shown limited success or are pending." (PMID 40826256, 2025). "Although tauopathies are a predominant feature of AD, a causative link between MAPT mutations and AD has not been identified." (PMID 40771194, 2025). "The MAPT gene exhibits over 80 identified mutations associated with various tauopathies, yet no unified mechanism explains tau mutation effects, resulting in phenotypic heterogeneity and therapeutic development challenges (De wit and Ghosh, 2016)." (PMID 41399730, 2025). "MAPK1 emerged as a central regulatory node, influencing the expression of nearly one-third of proteins in the FTD-specific network and directly modulating MAPT and complement system proteins, emphasizing the importance of kinase dysregulation in tauopathy progression." (PMID 40665052, 2025). "Besides the direct overlaps between MAPT and SNCA, tauopathies and synucleinopathies also share common pathogenic pathways." (PMID 38528629, 2024). "The strong association of PSP and other tauopathies with common variation in the 17q21.31 locus in the absence of a MAPT coding region mutation favors genetic regulatory mechanisms as a causal driver." (PMID 39154163, 2024). "In the case of oligodendrocyte-specific MAPT expression, the highest transcript was found in the frontal white matter and lowest in the cerebellar white matter, pointing to the region-specific vulnerability of the brain in tauopathy." (PMID 38994964, 2024). "Previous metabolomic approaches to study tauopathy and MAPT mutations took a general view of metabolism rather than focusing on the impact of ROS and formation of oxidised lipid species." (PMID 38790613, 2024). "Moreover, in human AD, mouse, and in vitro tauopathy models expressing mutant MAPT, increased p-tau levels resulted in decreased SNHG8 expression, increased stress granule formation, and elevated cytotoxic granule-associated RNA binding protein TIA1." (PMID 38726308, 2024). "There are also cases of MAPT mutation working independently of SNCA to cause Parkinsonism, showing the possibility that some tauopathies may share pathogenic pathways with synucleinopathies." (PMID 38528629, 2024).